WNT1 (Wnt family member 1)
Diseases named in the same sentence as WNT1 in open-access papers (continued):
Sharing a sentence is not in itself a finding about the gene and the disease.
Adrenal insufficiency (1 paper, 2013). Insufficient production of steroid hormones (primarily cortisol) by the adrenal glands. "Complete sex reversal in 46,XY males without adrenal insufficiency can also occur in conditions such as Leydig cell hypoplasia or due to mutations in SRY, DHH, SOX9, DMRT1, WNT1, or ATRX." (PMID 23748066, 2013).
Alagille syndrome (1 paper, 2021). "Deleting Jagged1 in the cranial neural crest (CNC) causes (Wnt1-cre, Jag1 Flox/Flox) mice die at postnatal day 30 due to an inability to masticate, owing to jaw misalignment and poor occlusion, recapitulating the midfacial hypoplasia phenotype of Alagille syndrome." (PMID 34039391, 2021).
ameloblastoma (1 paper, 2024). The most common odontogenic tumor, arising from the epithelial component of the embryonic tooth and usually affecting the molar-ramus region of the mandible or maxilla. "Todos estos resultados sugieren que Wnt1 es una molécula de señalización clave para el desarrollo del ameloblastoma." (PMID 39444727, 2024).
ampullary cancer (1 paper, 2020). "The most frequent gene alteration in ampullary cancer was found in APC (23%), followed by CTNNB1 (9%), RNF43 (8%), CDH1 (1.9%), and WNT1 (1.3%)." (PMID 32764696, 2020).
asthma (1 paper, 2021). "Wnt1 was able to reduce airway allergic inflammation and the hyperresponsiveness of asthma by inhibiting the activation of pulmonary dendritic cells." (PMID 34737744, 2021).
attention deficit-hyperactivity disorder (1 paper, 2024). A disorder characterized by a marked pattern of inattention and/or hyperactivity-impulsivity that is inconsistent with developmental level and clearly interferes with functioning in at least two settings (e.g. at home and at school). "Impairment in the Wnt pathway has been associated with various psychiatric disorders in humans, such as WNT1, WNT2, and WNT7A in autism spectrum disorder, WNT7B and LRP5 in SCZ, and LRP5 and LRP6 in attention-deficit/hyperactivity disorder." (PMID 39452096, 2024).
bone sarcoma (1 paper, 2015). A sarcoma that arises from the bone. "In this study, we found that five of six canonical Wnt ligands (Wnt1, 3, 3a, 8b and 10b) in bone sarcoma cells were prominently increased, while Wnt2 expression was remarkably decreased." (PMID 25999350, 2015).
Brachycephaly (1 paper, 2016). An abnormality of skull shape characterized by a decreased anterior-posterior diameter. "At postnatal day (P) 1, all (16 of 16) Hand2CAT/+; Wnt1-Cre (hereafter Hand2NC) mice died neonatally with craniofacial deformities, including brachycephaly, eyelid colobomas, tongue protrusion, and small pinna in the anterior position, compared to control littermates." (PMID 27329940, 2016).
Brain atrophy (1 paper, 2021). Partial or complete wasting (loss) of brain tissue that was once present. "More specifically, while two 3-year-old children with WNT1 mutations displayed a severe neurological phenotype with brain atrophy, two other children, aged 11 and 19 years, only had skeletal affection, and no further neurological diagnostics were initiated for these patients." (PMID 34759273, 2021).
cardiac hypertrophy (1 paper, 2021). "Our study provides evidence indicating miR-128 as an inducer of HF and cardiac hypertrophy by enhancing Wnt1/β-catenin in an Axin1-dependent nature." (PMID 34965835, 2021).
carotid artery aneurysm (1 paper, 2025). "4-OHT treatment at E8.5 and E9.5, which coincides with the timing of Wnt1-Cre2 activity, induced severe vascular defects, including carotid artery aneurysm by E13.5." (PMID 40456777, 2025).
cataract (1 paper, 2018). Partial or complete opacity of the crystalline lens of one or both eyes that decreases visual acuity and eventually results in blindness. "Additionally, the mRNA of Wnt ligands was assayed by RT-qPCR, and Wnt4 and Wnt5a ligands were upregulated in K14E6 cataracts, whereas Wnt1, 3a, 7a, and 8a, were downregulated." (PMID 29888254, 2018).
cervical squamous cell carcinoma (1 paper, 2020). A squamous cell carcinoma arising from the cervical epithelium. "Here, we aimed to identify the oncogenic potential and clinical significance of a known miR-34a target, WNT1, in cervical squamous cell carcinoma (SCC) development and to investigate the associated mechanisms underlying cervical SCC cell proliferation and invasion." (PMID 32301035, 2020).
chronic myeloid leukemia (1 paper, 2014). "ABCB1, which is known to be responsible for drug resistance in chronic myeloid leukemia (CML), decreases in expression levels after treating with β-catenin and Wnt1 shRNA." (PMID 25401518, 2014).
colorectal polyps (1 paper, 2024). "We utilized qRT-PCR to measure miR-200, miR-494, TET1, and Wnt1 mRNA levels in colorectal polyps, actual colorectal tumors, and normal adjacent tissues." (PMID 39495308, 2024). "This study aimed to evaluate the expression level of selective miRNAs (miR-200 and miR-494), TET1, and Wnt1 in colorectal polyps, actual colorectal tumors, and normal adjacent tissues." (PMID 39495308, 2024).
coronary artery disease (1 paper, 2023). "We aimed to evaluate the levels of these miRNAs, WNT-proteins (WNT1, -3a, -4, -5a), and LRP6 in adults with coronary artery disease against a control population." (PMID 38139440, 2023).
Crohn disease (1 paper, 2023). A gastrointestinal disorder characterized by chronic inflammation involving all layers of the intestinal wall, noncaseating granulomas affecting the intestinal wall and regional lymph nodes, and transmural fibrosis. "For example, Crohn’s disease patients showed reduced HD5 and -6 levels, which were associated with decreased Tcf1, Tcf4, and LRP6, along with reduced Wnt signaling molecules Wnt1, -3, and -3a." (PMID 37762180, 2023).
cyst (1 paper, 2018). A sac-like closed membranous structure that may be empty or contain fluid or amorphous material.
Dyskinesia (1 paper, 2013). A movement disorder which consists of effects including diminished voluntary movements and the presence of involuntary movements. "Strikingly, CNQX infusion into the cerebellum of Wnt1-Cre;Itpr1flox/flox mice improved their voluntary movement significantly: dyskinesia such as opisthotonus, rigid posture, and tremor was abolished." (PMID 24109434, 2013).
Dystonia (1 paper, 2013). An abnormally increased muscular tone that causes fixed abnormal postures. "To examine whether altered IO activity was associated with dystonia in the Wnt1-Cre;Itpr1flox/flox mice, we pharmacologically inhibited IO activities." (PMID 24109434, 2013). "Thus, increase of CF frequency through IO activation may underlie the expression of dystonia in Wnt1-Cre;Itpr1flox/flox mice." (PMID 24109434, 2013). "To further delineate the neurons responsible for the expression of dystonia in Itpr1−/− and Wnt1-Cre;Itpr1flox/flox mice, we investigated the expression of cfos mRNA, a neural activity marker." (PMID 24109434, 2013). "This hypothesis is in line with our finding that infusion of AMPAR blocker in the cerebellum ameliorates dystonia in Wnt1-Cre;Itpr1flox/flox mice, because AMPA receptor blocker inhibits CF-PC synapse transmission." (PMID 24109434, 2013). "Wnt1-Cre;Itpr1flox/flox mice may provide a therapeutic dystonia model solely dependent upon abnormal neural activities within the cerebellum and brainstem." (PMID 24109434, 2013). "Thus, we propose that altered cerebellar activity causes dystonia by a mechanism, which does not involve BG activity in Wnt1-Cre;Itpr1flox/flox mice." (PMID 24109434, 2013). "It is also worth mentioning that the distinctive CSs appeared only in awake Wnt1-Cre;Itpr1flox/flox mice, and that altered activation of IO itself was not sufficient for generation of dystonia, since harmaline, which evokes similar CS dominant spike patterns of PCs, does not cause dystonia." (PMID 24109434, 2013).
endometrial polyp (1 paper, 2024). A benign nodular lesion protruding above the surface of the endometrium. "According to a previous study, endometrial polyp tissues have an increased expression of WNT1." (PMID 38473810, 2024).
endothelial dysfunction (1 paper, 2025). In vascular diseases, endothelial dysfunction is a systemic pathological state of the endothelium (the inner lining of blood vessels) and can be broadly defined as an imbalance between vasodilating and vasoconstricting substances produced by (or acting on) the endothelium. "Activation of the Wnt signaling pathways through Wnt1 and Wnt5a contributes to endothelial dysfunction and inflammation through the release of pro-inflammatory cytokines and the proliferation of ECs, while Wnt1 and Wnt4 have been shown to be involved in VSMC proliferation." (PMID 39941130, 2025).
esophageal squamous cell carcinoma (1 paper, 2022). Esophageal squamous cell carcinoma (ESCC) is a type of esophageal carcinoma (EC) that can affect any part of the esophagus, but is usually located in the upper or middle third. "miR-301a targets the tumor-promoting factor WNT1 to increase the radiosensitivity of esophageal squamous cell carcinoma (ESCC) cells, while suppressing drug resistance and EMT by targeting Snail and Vimentin." (PMID 35805066, 2022).
glaucoma (1 paper, 2021). Increased pressure in the eyeball due to obstruction of the outflow of aqueous humor. "Using neural crest-specific Wnt1-cre, we have shown that deletion of Angpt1 in the uveal tract recapitulates the glaucoma phenotype of whole-body knockouts, confirming the TM origin of SC-regulating ANGPT1." (PMID 34663817, 2021).
hamartoma (1 paper, 2023). A benign and excessive tumor-like growth of mature cells and normal tissues which grow in a disorganized pattern. "The results suggest that Wnt-1/β-catenin signaling is essential for toothmorphogenesis and cell differentiation and that shifts in the expression of theseproteins between odontogenic epithelium/ectomesenchyme can cause developmentaldisorders, leading to the development of hamartomas." (PMID 38133085, 2023). "The lowest expression of Wnt-1/β-catenin was observed in the epithelialcomponent of odontomas that are hamartomas, where less organization or fewer changesin their structure are expected." (PMID 38133085, 2023).
Hepatic steatosis (1 paper, 2023). Steatosis is a term used to denote lipid accumulation within hepatocytes. "Transgenic mice (overexpress Wnt1 in hepatocytes, Wnt+) mice and wild-type littermates were given high fat diet (HFD) for 12 weeks to induce hepatic steatosis." (PMID 38152126, 2023).
hepatoblastoma (1 paper, 2019). Hepatoblastoma (HB) is a malignant hepatic tumor and is the most common pediatric liver cancer. "It was revealed that morpholino oligonucleotides inhibited NF-kB activation in human hepatoblastoma cell line (HepG2 cells) and decreased Wnt-1 production." (PMID 31511432, 2019). "Accordingly, it may be suggested that the activation of NF-kB may increase the production of Wnt-1, which triggers the activation of Wnt/β-catenin to induce the development of hepatoblastoma." (PMID 31511432, 2019).
hyperglycaemia (1 paper, 2022). "Similarly, treatment with Tripterygium wilfordii significantly inhibited the hyperglycaemia-induced expression of Wnt1 and β-catenin at both the mRNA and protein levels in diabetic rats induced by streptozotocin." (PMID 36059935, 2022).
hyperlipidemia (1 paper, 2015). "Reduced plasma levels of Wnt1 and elevated levels of LRP6 antagonists have been reproducibly associated with the risk for CAD in patients with early onset CAD, diabetes, and hyperlipidemia in several large clinical studies." (PMID 26046396, 2015). "Furthermore, low plasma levels of Wnt1 and high plasma levels of the LRP6 antagonists sclerostin and DKK1 have been associated with the risks for hyperlipidemia and atherosclerosis." (PMID 26046396, 2015).
invasive carcinoma (1 paper, 2011). A carcinoma that is not confined to the epithelium, and has spread to the surrounding stroma. "TWIST1 can be regulated by multiple extracellular factors through PI3K/AKT, Wnt1 and NF-κB pathways in invasive carcinoma concordant with our observations that activation of AKT by ARTN leads to increased expression of TWIST1 in ER-MC cells." (PMID 22060274, 2011).
Keratocystic odontogenic tumor (1 paper, 2017). An intraosseous odontogenic neoplasm that usually arises from the mandible. "It is noteworthy that an overexpression of Wnt1 was similarly identified in keratocystic odontogenic tumor, a common and benign OT that may also have an aggressive behavior." (PMID 28149478, 2017).
kidney injury (1 paper, 2022). Trauma to the kidney. "In summary, we have demonstrated that Wnt signaling, especially Wnt1 and Wnt3a, plays a pivotal role in mediating HFD-induced kidney injury." (PMID 35462998, 2022).
large cell lung carcinoma (1 paper, 2012). "The same regulatory effects of SOX2 on the expression of WNT1, WNT2, NOTCH1 and c-MYC were also observed in the human large cell lung carcinoma cell line H460 with SOX2 silencing.This finding indicates a universal regulatory mechanism of SOX2 on the oncogene network of both human lung cell lines." (PMID 22615765, 2012).
laryngeal carcinoma (1 paper, 2021). Carcinoma that arises from the laryngeal epithelium. "The limitation of this study is that the mechanism that the NK4 gene affects the occurrence and development of laryngeal cancer may be related to the regulation of the DKK1/Wnt1/β-Catenin related pathways, which needs to be demonstrated by further experiments." (PMID 34970492, 2021).
leukoplakia (1 paper, 2007). A white patch or plaque on a mucous membrane that cannot be characterized clinically or pathologically as any other disease. "No signal was detectable with antibodies against Wnt1 and Wnt7a in normal and leukoplakia epithelia, whereas Wnt5a signal was ubiquitously detectable in normal oral epithelium, leukoplakia, and in OSCC (data not shown)." (PMID 17922924, 2007).
lipid metabolism disorder (1 paper, 2023). "Reconstitution of Sirt6 recruited using SNF2H suppressed Wnt1 expression and improved lipid metabolism disorder by promoting lipophagy." (PMID 37736721, 2023).
liver cirrhosis (1 paper, 2023). "In 2018, it was confirmed that vitamin D can silence the Wnt1/β-catenin pathway, which suppresses the activation of hepatic stellate cells and reduces collagen fiber secretion, leading to the inhibition of type I/III collagen formation, thereby ameliorating the deterioration of liver cirrhosis." (PMID 37426183, 2023).
lymph node metastasis (1 paper, 2020). "We found that increased WNT1 expression was significantly associated with different HR-HPV types (p = 0.035), FIGO stage (p = 0.042), depth of stromal invasion (p = 0.003), lymph vascular space invasion (LVSI) (p = 0.020) and lymph node metastasis (LNM) (p = 0.011)." (PMID 32301035, 2020).
malignant glioma (1 paper, 2015). A grade III or grade IV glioma arising from the central nervous system. "Malignant glioma growth may involve activation of the Wnt-1 signaling pathway, however, the specific underlying mechanism requires further investigation." (PMID 25435937, 2015).
microphthalmia (1 paper, 2023). Congenital or developmental anomaly in which the eyeballs are abnormally small. "With respect to craniofacial defects, we observed tectal hypertrophy, enlarged forebrain and facial defects, initially observed at E13.5, including microphthalmia/anophthalmia and microtia, some of which were phenocopied in Gpr161 cKO mice with Wnt1-Cre in our previous study." (PMID 37885410, 2023).
migraine (1 paper, 2025). "miR-34a-5p inhibits the Wnt1/β-catenin pathway, thereby modulating molecules related to the trigeminovascular system and exacerbating migraine." (PMID 41039196, 2025). "METTL3 contributes to migraine pathogenesis through m6A-dependent upregulation of miR-34a-5p, which suppresses the Wnt1/β-catenin axis and promotes TGVS activation." (PMID 41039196, 2025). "Overexpression of miR-34a-5p further aggravated migraine-related responses by inhibiting Wnt1 signaling." (PMID 41039196, 2025). "Our study demonstrates that METTL3, a key m6A methyltransferase, is significantly upregulated in migraine and contributes to disease progression by promoting the maturation of miR-34a-5p and regulating the Wnt1/β-catenin pathway." (PMID 41039196, 2025). "While our study highlights the METTL3/miR-34a-5p/Wnt1 signaling axis as a key contributor to TGVS activation in migraine, we acknowledge that METTL3 may exert additional effects through alternative mechanisms." (PMID 41039196, 2025). "In addition, silencing of miR-34a-5p can activate Wnt1/β-catenin and reduce migraine mediated by the TGVS activation." (PMID 41039196, 2025). "However, whether METTL3 upregulates the expression of miR-34a-5p by mediating m6A methylation modification of pri-miR-34a, and subsequently influences the pathogenesis of migraine through targeting Wnt1, remains to be elucidated." (PMID 41039196, 2025).
multicystic dysplastic kidney (1 paper, 2011). Multicystic dysplastic kidney (MCDK) is a congenital anomaly of the kidney and urinary tract (CAKUT) in which one or both kidneys (unilateral or bilateral MCDK respectively) are large, distended by multiple cysts, and non-functional. "The molecular events involved in multicystic dysplastic kidneys, in general, remain to be elucidated, though studies have suggested involvement of WNT-1, FGFR3, and PAX2." (PMID 21995344, 2011).
myeloma (1 paper, 2023). "To address this, we examined the impact of a novel anti‐LRP6 antibody that potentiates LRP6‐mediated Wnt1 class signaling in normal and myeloma‐burdened bone conditions." (PMID 36987921, 2023).
Norrie disease (1 paper, 2013). A rare X-linked genetic vitreoretinal condition characterized by abnormal retinal development with congenital blindness. "Genes annotated as inducers of wingless-type mouse mammary tumor virus (MMTV) integration site family members (Wnt) (for example, Norrie disease (Ndp)), several Wnt genes (for example, Wnt1) and all Wnt1-inducible signaling pathway proteins (Wisp1, Wisp2 and Wisp3) completed the LE of Cluster_01-02." (PMID 24286337, 2013).
omphalocele (1 paper, 2023). Omphalocele is an embryopathy classified in the group of abdominal celosomias and is characterized by a large hernia of the abdominal wall, centered on the umbilical cord, in which the protruding viscera are protected by a sac. "Wnt1-Cre deletion caused omphaloceles and craniofacial defects with complete penetrance." (PMID 38079449, 2023).
Osteopenia (1 paper, 2022). Osteopenia is a term to define bone density that is not normal but also not as low as osteoporosis. "The hypomorphic Wnt1 Swaying mouse model has a better neonatal survival rate than the total Wnt1-KO and it recapitulates several phenotypes of OI patients, such as spontaneous fractures and severe osteopenia, caused by a decrease in osteoblast activity." (PMID 35052478, 2022). "The heterozygous Wnt1-KO models suffered mild osteopenia but no significantly impaired bone resorption or formation, although osteoblast differentiation and activity were impaired in vitro." (PMID 35052478, 2022).
ovarian tumours (1 paper, 2014). "In ovarian tumour cells, WNT-1 expression was present in 31 (67.4%) women." (PMID 24499657, 2014). "We showed that in most of the ovarian tumours, there was a strong WNT-1 expression; however, no nuclear β-catenin was found." (PMID 24499657, 2014).
parathyroid tumors (1 paper, 2007). "WNT3 but not WNT1 was expressed by RT-PCR in parathyroid tumors." (PMID 18044981, 2007).